IL10 (interleukin 10)
Diseases named in the same sentence as IL10 in open-access papers (continued):
Sharing a sentence is not in itself a finding about the gene and the disease.
hypothyroidism (12 papers, 2019 to 2025). Abnormally low levels of thyroid hormone. "Hypothyroidism is closely associated with perturbation in IL-10 and IL-37." (PMID 40672362, 2025). "However, Kp-10 treatment reduced the higher IL-10 immunolabeling in the labyrinth zone caused by hypothyroidism, matching it to that of the control." (PMID 35966095, 2022). "TSH, TPOAb, CRP, percentage of Th17 cells, Th17/Treg ratio, IL-2, IL-6, IL-10 and TNFα levels increased significantly in the hypothyroidism group compared to the control group, and FT4 levels and percentage of Treg cells decreased significantly." (PMID 41573549, 2025). "Inversely, IL1β levels were increased in WSB/EiJ mice (by 110% compared to their control group, p < 0.05), whereas IL10 levels were unaffected in response to hypothyroidism (p < 0.05)." (PMID 39409121, 2024). "The serum levels of IL-2, TNF-α, and IFN-γ in the hypothyroidism group were significantly increased (p < 0.01, p < 0.001, p < 0.001, respectively), whereas the level of IL-10 was dramatically reduced (p < 0.001), compared to those in the control group." (PMID 37051293, 2023). "In the labyrinth zone, however, while hypothyroidism also increased the IL-10 labeling area when compared to the control (P<0.05), Kp10 treatment reduced IL-10 immunolabeling, matching it to that of the control group (P>0.05)." (PMID 35966095, 2022). "The reduced expression of IL-10, NOS2 and IFN-γ in the placenta of rats with hypothyroidism has supported this." (PMID 41282300, 2025). "We found that the CRP, IL-2, IL-4, IL-10, and TNF-α levels were greater in the hypothyroidism group than in the control group." (PMID 39185088, 2024). "The serum CRP, IL-2, IL-4, IL-10 and TNF-α levels in the hypothyroidism group were greater than those in the control group (P < 0.05)." (PMID 39185088, 2024). "Hypothyroidism patients had increased C-reactive protein (CRP), interleukin-2 (IL-2), IL-4, IL-10, and tumor necrosis factor (TNF)-α levels." (PMID 39185088, 2024). "The hypothyroidism group had higher serum IL-2, TNF-α, and IFN-γ levels, and lower IL-10 levels, than the control group." (PMID 37051293, 2023). "In addition, Bacteroides can boost antigen-specific Th1 cells to secrete IL-10 and limit the release of IFN-γ, thereby weakening the pathogenic potential of Th1 cells in the inflammatory response, which is related to the occurrence of hypothyroidism during pregnancy." (PMID 37051293, 2023). "The levels of TSH, hsCRP, IL-10, IL-6, TNF-α, TC, LDL, FFA and ApoB in the pregnancy hypothyroidism group were higher than those in the control group (P <0.05)." (PMID 36275023, 2022). "In this study, we found that the levels of hsCRP, IL-10, IL-6 and TNF-α in pregnant women with clinical hypothyroidism during pregnancy were significantly higher than those in the control group." (PMID 36275023, 2022). "Daily treatment with Kp-10 did not alter the higher protein expression levels of VEGF, HIF1α, IL10, GRP78, and CHOP caused by hypothyroidism in the junctional zone compared to control, nor the lower expression of Dio2 caused by hypothyroidism." (PMID 35966095, 2022).
keloid (12 papers, 2017 to 2026). An irregularly shaped, elevated mark on the skin caused by deposits of excessive amounts of collagen during wound healing. "Other interleukins, such as IL-1β and IL-10, have also been implicated in keloid pathogenesis through their interactions with the JAK-STAT pathway." (PMID 39201463, 2024). "We did not found any previously study associating the expression of IL-10 with keloids; however, in culture of fibroblasts from patients with scleroderma and normal skin, stimulated with IL-10, there was a decrease in collagen α1(I) mRNA expression in both groups." (PMID 28638180, 2017). "Another study described the therapeutic effect of interleukin-10 in keloid fibroblasts by suppression of TGF-β/Small mothers against the decapentaplegic (Smad) pathway." (PMID 39799030, 2025). "The study found that, compared with normal control, the proliferation of keloid fibroblasts was shown to be significantly suppressed on treatment with IL-10 in a time and dose-dependent manner." (PMID 39799030, 2025). "Conversely, IL-10 expression is decreased in keloids, and its overexpression has been found to decrease inflammation and promote regenerative healing." (PMID 39201463, 2024). "The putative protein biomarkers identified in this study (i.e., IL-10, TIMP-1, and fibronectin) have been shown to exhibit diagnostic properties in fully developed HTSs or keloids in humans." (PMID 29458433, 2018). "The expressions of mRNA for IFN-γ and IL-10 were significantly lower in patients with keloid compared to the controls." (PMID 28638180, 2017). "In the present study, we evaluated the percentages of total collagen and type I and type III collagens and the relative number of mRNA copies for TGF-β, IFN-γ, IFN-γR1, TNF-α, and IL-10 in keloid fragments compared to normal scars." (PMID 28638180, 2017). "Other cytokines, such as IL33, IL-13, IL-10 and IL-4 have also been noticed increased in keloids." (PMID 41556665, 2026). "One study showed that the expression of mRNA for IL-10 was lower significantly in keloid." (PMID 39799030, 2025). "IL-10 inhibited the proliferation of keloid fibroblasts and collagen synthesis, and also IL-10 could negatively modulate the TGF-β/Smad signaling pathway, preventing keloid fibroblasts from proliferation and collagen production." (PMID 39799030, 2025). "The expression of iNOS, IL-10, and IL-12 were higher in keloids." (PMID 35990663, 2022). "According to these results, the use of recombinant human (RH) IL-10 may be a potential treatment for keloid." (PMID 33959031, 2021). "In HS and keloid, there is a relatively large number of studies on IL-6, IL-10 and IL-1β." (PMID 33959031, 2021). "Furthermore, in this study, patients with keloid showed mRNA expression for IL-10 significantly lower compared to the controls." (PMID 28638180, 2017). "In addition, mast cells may also suppress local inflammatory responses by releasing anti-inflammatory cytokines (such as IL-10), thereby slowing down the proliferation of keloids." (PMID 40718487, 2025). "Similarly, blocking of IL-10 has been shown to decrease keloid scar formation." (PMID 34445173, 2021). "In keloids, TGF-β upregulates the expression of anti-inflammatory cytokines like IL-10 while downregulating the levels of pro-inflammatory cytokines such as IL-6 and TNF-α, thus regulating the local immune microenvironment." (PMID 40718487, 2025). "These cells participate in various aspects of immune regulation during the development of keloids, such as the release of inflammatory mediators (e.g., interferon-γ(IFN-γ), IL-2, IL-6, TNF-α, IL-6, IL-10), as well as cell proliferation and migration." (PMID 40718487, 2025). "However, although some microenvironmental factors may disrupt the balance of TGF -β/IL-10, the precise regulatory mechanism of Tregs’ dual function and the key critical points that facilitate their pro fibrotic activity in keloids are still not fully understood." (PMID 40718487, 2025).
keloid (continued). "In another study, gene expression levels of IL-12 and iNOS or IL-10 and TGF-β were used to identify M1 and M2 macrophages, respectively, in macrophages isolated via enzymatic digestion of the keloid scar tissue (unspecified scar age)." (PMID 31187196, 2019). "To investigate the potential of IL‐10 delivery via ADSCs to promote myofibroblast regression in vitro, we evaluated the changes in α‐smooth muscle actin (α‐SMA) and TGF‐β1 expression in human keloid‐derived fibroblasts." (PMID 38435824, 2024). "With redox balance, TGF-β inhibits the production of pro-inflammatory cytokines such as TNF-α, IL-1β, and IL-6, stimulates IL-10, allows the differentiation of fibroblasts into myofibroblasts to help cover wounds, inhibits the TGF-β/Smad pathway and consequently reduces fibrosis and keloids." (PMID 39061892, 2024). "Thereby, our findings indicate that IL-10 may play a role in the pathogenesis of keloids with negative correlation between the collagen type III and IL-10 expression can be related to this low IL-10 expression in keloids." (PMID 28638180, 2017). "Significantly, the expression of mRNA for TGF-β in keloid was increased, the expressions of IFN-γ, IFN-γR1, and IL-10 were lower, and IFN-γR1 and TNF-α had no statistical difference." (PMID 28638180, 2017).
measles (12 papers, 2011 to 2024). A highly contagious viral infection caused by the measles virus. "In this study, several SNPs in retinoic acid receptor α (RARB) were associated with variations in both measles antibodies and cytokine secretion levels, including IL-10, IFN-α, and TNF-α." (PMID 33167413, 2020). "A different polymorphism (rs11265452) in the SLAM gene previously associated with measles antibody levels (p = 0.04) exhibited a significant association with measles-specific IL-10 production (p = 0.0008)." (PMID 22241978, 2011). "In the candidate gene study, two SNPs in SLAM were associated with measles antibody levels, as well as the IFN-γ and IL-10 responses." (PMID 33167413, 2020). "In our study, a majority (4 out of 6) of GH-SH animals were able to produce measles specific IL-10 compared to GH-PH animals (2 out of 6)." (PMID 33178191, 2020). "Scarce studies on measles lung LIR indicated depletion of IL-10+ and IL-12+ cells in infected children; however, there was a greater number of IL-1+, IFN+, and IL-4+ cells." (PMID 30936878, 2019). "There was a negative correlation between postvaccination Tregs and the IFN-γ:IL-10 ratio in TT cultures (p = 0.0202, r = −0.471) and measles peptide cultures (p = 0.0475, r = −0.4001) in the DTP group only." (PMID 28855899, 2017). "Two previously reported promoter IL10 and IL2 SNPs (rs1800890 and rs2069762) demonstrated associations with measles-specific cellular response (p < 0.03)." (PMID 22241978, 2011). "Likewise, in measles patients, increased IL-10 levels were observed in blood samples in the acute stage of disease." (PMID 37112814, 2023). "Furthermore, significant associations were shown between multiple vitamin D receptors (VDR) and retinoid X receptor α (RXRA) SNPs/haplotypes and measles-specific IL-2, IL-6, IL-10, IFN-α, IFN-γ, IFNλ-1, and TNF-α cytokine secretion." (PMID 33167413, 2020). "However, longitudinal analysis of RU486 treated patients showed a significant increase in IL-10 response to measles whole lysate." (PMID 29973928, 2018). "Moreover, induction of IL-10 by infected DCs is supposed to suppress Th1 and prolong Th2 immune responses in measles patients, which leads to ineffective immunity." (PMID 24769532, 2014). "For example, HLA class I and HLA class II genotypes and SNPs in cytokine/cytokine receptor genes (IL12B, IL12RB1, IL2, IL10) and the cell surface measles virus receptor the CD46 gene, have been reported to affect measles vaccine-induced immunity." (PMID 34683414, 2021). "The inverse correlation between the circulating CD4+FOXP3+CD127− Tregs post-DTP vaccination and the postvaccination IFN-γ:IL-10 ratio in TT and measles peptide cultures, but not PPD or αCD3/αCD28, may support a vaccine-specific immunoregulatory role." (PMID 28855899, 2017).
non-alcoholic fatty liver disease (12 papers, 2011 to 2026). "Bifidobacterium promotes immunomodulation by stimulating interleukin-10-producing dendritic cells, while Lactococcus and Gordonibacter have been implicated in metabolic protection and non-alcoholic fatty liver disease improvement." (PMID 40565319, 2025). "In methionine-choline deficiency (MCD)-induced Non-Alcoholic Fatty Liver Disease (NAFLD), the OCTN2 substrate betaine might reduce liver inflammation and damage, at least partly, by improving the balance between proinflammatory (TNF, IL-6) and anti-inflammatory (IL-10, TGF-β) cytokines." (PMID 38672410, 2024). "The non-traditional cardiovascular risk factors that we studied were the following: hs-CRP, TG/HDL ratio, ApoA1, ApoB, ApoB/ApoA1 ratio, leptin, adiponectin, homocysteine, IL-2, IL-4, IL-6, IL-10, IL-17A, TNF-α and INF-γ, and non-alcoholic fatty liver disease (NAFLD)." (PMID 37892418, 2023). "Higher hepatic TNF-α (P<0.0001) and IL-10 (P=0.001) mRNA levels were found in RBD-challenged mice, although without detectable non-alcoholic fatty liver disease." (PMID 32401929, 2020).
Osteopenia (12 papers, 2012 to 2024). Osteopenia is a term to define bone density that is not normal but also not as low as osteoporosis. "Experiments have shown that IL-10 deficiency can cause adverse outcomes in bone, such as attenuating bone formation and progressing osteopenia in animal models." (PMID 37393312, 2023). "As for the anti-inflammatory cytokine IL-10, its deficiency is associated with osteopenia, decreased bone formation, and the mechanical fragility of bones." (PMID 30669348, 2019). "The importance of IL-10 in bone metabolism was demonstrated in IL-10 deficient mice, which develop osteopenia and decreased bone formation." (PMID 22724005, 2012). "A deficit of IL-10 results in osteopenia, mechanical fragility of bones and defects in their formation." (PMID 27144532, 2016). "The central role of IL-10 in promoting bone growth and accelerating fracture healing is further supported by studies showing that IL-10 regulates bone resorption, and its absence leads to osteopenia, mechanistic fragility, and malunion." (PMID 26000315, 2015). "Bone marrow-derived macrophages from IL-10−/− mice displayed an impaired induction of autophagic pathway upon LPS stimulation, implicating selective local activation of autophagy, i.e., in gut or bone, may explain osteopenia shown in IL-10−/− mice." (PMID 31847438, 2019). "Additionally, it is well documented that the production of local and circulating pro-inflammatory cytokines, including TNF-α, IL6, and IL10, plays an important role in the occurrence and development of osteopenia by inhibiting osteoblast function and promoting osteoclast differentiation." (PMID 30819183, 2019).
urticaria (12 papers, 2010 to 2025). A vascular reaction of the skin characterized by erythema and wheal formation due to localized increase of vascular permeability. "However, here, we focus on some studies that found an association between polymorphisms of IL10 and aspirin sensitization in asthmatic patients and patients with urticaria." (PMID 35456412, 2022). "IL-10 is also associated with IL-5 in urticaria as well as those showing skin and rhinitis." (PMID 20616938, 2010). "Lower serum levels of anti‐inflammatory IL‐1RA, and chemokines IL‐8 and MCP‐1, and higher levels of anti‐inflammatory IL‐10, were detected at baseline prior to treatment in those patients who subsequently experienced urticaria." (PMID 40045925, 2025). "When the patients were grouped based on the urticaria severity (mild, moderate and severe), IL-10 levels were significantly higher in patients with severe disease activity compared to patients with mild disease activity (p = 0.047)." (PMID 38795119, 2024). "Urticaria is mediated by mixed T helper (Th) 1/Th2-reactive lymphocytes, with Th1 cells primarily secreting IL-2 and Th2 cells secreting IL-10." (PMID 37954607, 2023). "In patients with urticaria, there is an observed increase in IL-10 production and a decrease in IL-2 levels, consistent with the findings of the present study." (PMID 37954607, 2023). "Since now there is no study in the literature describing the levels of all four ILs (IL-4, IL-6, IL-8 and IL-10) in the patients with urticaria." (PMID 24578755, 2014). "Our study concerns four ILs, IL-4, IL-6, IL-8 and IL-10, simultaneously and their quantitative changes during the acute phase of urticaria as well as 2 weeks after drug administration." (PMID 24578755, 2014). "In patients showing urticaria, there is a positive correlation of IL-4 with IL-5, while that of IL-5 with IL-10." (PMID 20616938, 2010). "At day 90, only 3 of the patients with the extreme cytokine value had an AR; the patients with the highest levels of IL-10 and IL-17A experienced grade 1 toxicities (urticaria and AR, respectively), while the patient with the highest levels of CXCL9 experienced grade 3 urticaria." (PMID 29967609, 2018). "Nevertheless, the unaffected degranulation and suppressed secretion of IL-10 may be the reason that ST is commonly used with other herbs when treating allergic skin diseases; for example, ST is a part of a complicated herbal network for the treatment of urticaria." (PMID 29849717, 2018). "Notably, our meta-analysis clarified for the first time the effects of probiotics on IL-10 and IFN-γ in patients with urticaria, filling the gap in previous meta-analyses." (PMID 41450942, 2025). "We identified distinct cytokine signatures specific for urticaria and T-cell-mediated cutAEs, as well as an increase in IL-10 in non-responders during cutAEs." (PMID 38539560, 2024). "There have been studies evaluating the levels of isolated ILs in patients with urticaria, but none of them compared the levels of the four ILs in the same patient (IL-4, IL-6, IL-8 and IL-10)." (PMID 24578755, 2014). "It is not yet understood what is the specific role of IL-10 in urticaria, and still remain unclear this increase/decrease in IL-10 is a consequence of onset of CSU or compensatory response." (PMID 29299028, 2017).